IGHV1-46 (immunoglobulin heavy variable 1-46)
Description:
V region of the variable domain of immunoglobulin heavy chains that participates in the antigen recognition. Immunoglobulins, also known as antibodies, are membrane-bound or secreted glycoproteins produced by B lymphocytes. In the recognition phase of humoral immunity, the membrane-bound immunoglobulins serve as receptors which, upon binding of a specific antigen, trigger the clonal expansion and differentiation of B lymphocytes into immunoglobulins-secreting plasma cells. Secreted immunoglobulins mediate the effector phase of humoral immunity, which results in the elimination of bound antigens. The antigen binding site is formed by the variable domain of one heavy chain, together with that of its associated light chain. Thus, each immunoglobulin has two antigen binding sites with remarkable affinity for a particular antigen. The variable domains are assembled by a process called V-(D)-J rearrangement and can then be subjected to somatic hypermutations which, after exposure to antigen and selection, allow affinity maturation for a particular antigen.
Synonyms: IGHV146
Tractability: Antibody: UniProt places it where antibodies can reach, with medium confidence; UniProt predicts a signal peptide or a membrane-spanning region; its Gene Ontology location is reachable by antibodies, with medium confidence. PROTAC: ubiquitination databases record sites on it.
Gene: Immunoglobulin variable (V) gene on chromosome 14 (106,511,117 to 106,511,856, reverse strand). Ensembl gene ENSG00000211962.
Subcellular location: Secreted; Cell membrane
Pathways (Reactome):
Immune System: Antigen activates B Cell Receptor (BCR) leading to generation of second messengers; CD22 mediated BCR regulation; Classical antibody-mediated complement activation; FCERI mediated Ca+2 mobilization; FCERI mediated MAPK activation; FCERI mediated NF-kB activation; FCGR activation; Fc epsilon receptor (FCERI) signaling; Immunoregulatory interactions between a Lymphoid and a non-Lymphoid cell; Initial triggering of complement; Regulation of Complement cascade; Regulation of actin dynamics for phagocytic cup formation; Role of LAT2/NTAL/LAB on calcium mobilization; Role of phospholipids in phagocytosis
Disease: FCGR3A-mediated IL10 synthesis; FCGR3A-mediated phagocytosis; Potential therapeutics for SARS
Hemostasis: Cell surface interactions at the vascular wall
Vesicle-mediated transport: Scavenging of heme from plasma
Gene Ontology:
Molecular function: antigen binding
Biological process: immune response; immunoglobulin mediated immune response
Cellular component: extracellular region; plasma membrane
Homologues: Orthologues: macaque IGHV1-46 (70% identical), mouse Ighv1-4 (68% identical), mouse Ighv1-7 (68% identical), mouse Ighv1-50 (68% identical), mouse Ighv1-74 (68% identical), mouse Ighv1-53 (67% identical), mouse Ighv1-64 (67% identical), mouse Ighv1-55 (66% identical), mouse Ighv1-59 (66% identical), mouse Ighv1-66 (66% identical), mouse Ighv1-69 (66% identical), mouse Ighv1-77 (66% identical), and 48 more. Paralogues in human: IGHV1-2 (85% identical), IGHV1-3 (85% identical), IGHV1OR15-1 (84% identical), IGHV1-18 (81% identical), IGHV1OR21-1 (79% identical), IGHV1-24 (78% identical), IGHV1-69 (78% identical), IGHV1-69D (78% identical), IGHV1OR15-9 (78% identical), IGHV1-45 (76% identical), IGHV1-69-2 (75% identical), IGHV1-58 (74% identical), and 65 more.